ANGPTL8 (angiopoietin like 8)
Diseases named in the same sentence as ANGPTL8 in open-access papers (continued):
Sharing a sentence is not in itself a finding about the gene and the disease.
liver fibrosis (8 papers, 2021 to 2025). "When studying the role of ANGPTL8 (also known as lipasin) in the progression of liver fibrosis, it was found that ANGPTL8 is a secreted protein that is highly expressed in the liver during eating and lowly expressed during fasting." (PMID 39359922, 2024). "On the other hand, another study suggested that ANGPTL8 is a proinflammatory factor that accelerates liver fibrosis through its receptor LILRB2 and downstream ERK signaling pathways in the context of high fat diet-induced inflammatory activity." (PMID 37634084, 2024). "Since HSCs also contribute to liver fibrosis, we also investigated the role of the ANGPTL8/LILRB2 axis in HSC-MDM crosstalk if exists." (PMID 37481670, 2023). "Studies have shown that ROS can regulate the ERK signaling pathway to promote the proliferation of HCC cells, and our previous study demonstrated that ANGPTL8 promotes liver fibrosis in NAFLD through the ERK pathway." (PMID 37188659, 2023). "Serum ANGPTL8 levels could serve as a potential and specific diagnostic marker for liver fibrosis, and targeting ANGPTL8 shows significant promise in the development of novel therapies for treating NAFLD-related liver fibrosis." (PMID 40995256, 2025). "The livers from WT mice were more fibrotic than those from ANGPTL8-KO mice, and CCL4 upregulated the expression of ANGPTL8 in mouse livers, suggesting that ANGPTL8 promotes the progression of CCL4-induced liver fibrosis." (PMID 37188659, 2023). "ANGPTL8 has proinflammatory functions, and our previous study showed that ANGPTL8 was upregulated in the serum of patients with hepatic fibrosis and was higher than that in patients with HCC; however, a previous study did not explore the role of ANGPTL8 in hepatocarcinogenesis." (PMID 37188659, 2023).
Nephropathy (8 papers, 2021 to 2025). A nonspecific term referring to disease or damage of the kidneys. "Elevated levels of ANGPTL4 contribute to vascular permeability, a hallmark of diabetic retinopathy, while ANGPTL8 has been linked to nephropathy progression." (PMID 40137149, 2025). "The proven association between Ang2 and nephropathy, as well as the link between ANGPTL8 and renal dysregulation, and the presence of a positive correlation between Ang2 and ANGPTL8 all point to a possible interplay between these proteins contributing to DN’s progression or severity." (PMID 38790911, 2024). "Additionally, the ROC curve analysis indicated the sensitivity and specificity of using Ang2 in combination with ANGPTL8 as a diagnostic tool for people with DN, suggesting their potential as significant predictors for nephropathy in patients with T2D." (PMID 38790911, 2024). "Whether ANGPTL8 is a protective regulator or a risk factor in kidney disease remains to be explored." (PMID 34167540, 2021). "The increase in ANGPTL8 correlated with the clinical parameters of nephropathy in the same population with DN." (PMID 38790911, 2024). "Finally, the ROC analysis of the amalgamation of Ang2 and ANGPTL8 accentuates the significance of these proteins as prospective indicators for the progression into a state of nephropathy in people with T2D." (PMID 38790911, 2024). "Our previous study also found that circulating ANGPTL8 levels were negatively correlated with the eGFR, which indicates that ANGPTL8 may play a potential role in the progression of kidney disease." (PMID 34167540, 2021). "However, whether ANGPTL8 exerts an effect on the progression of nephropathy or whether it responds to renal dysfunction remains an open question." (PMID 34167540, 2021). "Additionally, the team found a positive correlation of ANGPTL8 with serum creatinine and a negative correlation with eGFR and urinary creatinine in people with nephropathy, making this adipokine a possible regulator in the development of nephropathy." (PMID 40137149, 2025).
polycystic ovary syndrome (8 papers, 2016 to 2021). A disorder that manifests as multiple cysts on the ovaries. "It is reported that circulating ANGPTL8 levels is increased in patients with polycystic ovary syndrome, partly because of the levels of sex hormone." (PMID 29940978, 2018). "New data is emerging to link ANGPTL8 to other diseases such as cancer and polycystic ovary syndrome will increase our knowledge of the functional role of this hormone." (PMID 27672665, 2016). "In addition, in other diseases, such as polycystic ovary syndrome (PCOS), adriamycin cardiomyopathy, and renal dysfunction, ANGPTL8 was also identified as a relevant modulator, which suggested additional functions of ANGPTL8 beyond the impacts on lipid and glucose metabolism." (PMID 29719529, 2018).
steatosis (7 papers, 2017 to 2025). Increased lipid within the cytoplasm of cells. "This systematic review and meta-analysis present the most up-to-date and comprehensive synthesis of current evidence on the association of circulating ANGPTL8 to steatosis/steatohepatitis, having searched for eligible studies under all relevant terms (i.e., NAFLD, MAFLD and MASLD)." (PMID 40276549, 2025). "However, the number of eligible studies in each of these subgroups is only two, hence more studies are required to clarify the potential association of circulating ANGPTL8 levels to the severity of steatosis/steatohepatitis." (PMID 40276549, 2025). "However, the potential association between circulating ANGPTL8 with steatosis/steatohepatitis has yet to be established due to inconsistent study results and the recent changes to the diagnostic definition of MAFLD and MASLD." (PMID 40276549, 2025). "Another study highlighted the link between triglyceride regulation by ANGPTL8 and its emergence as a potential novel biomarker for steatosis/steatohepatitis." (PMID 40725697, 2025). "ANGPTL8 reduces triglyceride clearance and promotes ectopic lipid accumulation, which can contribute to steatosis and its downstream complications." (PMID 40276549, 2025). "ANGPTL8 reduced the steatosis (p < 0.05) and mRNA expression levels of PPARG2, SREBF1, MOGAT2 and DGAT1 lipogenic genes of palmitate-treated hepatocytes." (PMID 34884755, 2021). "Advancing our understanding of the role of ANGPTL8 in the context of this chronic liver disease may also pave the way for innovative therapeutic approaches for patients with steatosis/steatohepatitis which would target ANGPTL8-related pathways." (PMID 40276549, 2025). "Elevated ANGPTL8 levels in earlier steatosis/steatohepatitis stages may exacerbate disease progression through inhibitory effects on the lipoprotein lipase activity." (PMID 40276549, 2025). "The present findings indicate that patients with NAFLD or MAFLD (no eligible study with a MASLD diagnosis was identified) exhibit higher circulating ANGPTL8 levels compared to controls, highlighting the potential of circulating ANGPTL8 as an additional novel biomarker for steatosis/steatohepatitis." (PMID 40276549, 2025). "Interestingly, ANGPTL8 inhibited steatosis and expression of lipogenic factors (PPARG2, SREBF1, MOGAT2 and DGAT1) in palmitate-treated human hepatocytes." (PMID 34884755, 2021). "Furthermore, the implication of ANGPTL8 in nuclear factor-κB (NF-κB) mediated inflammation and autophagy, may accelerate the transition from steatosis to fibrosis." (PMID 40276549, 2025). "Increased ANGPTL8 mRNA and protein levels and a positive correlation between ANGPTL8 mRNA and VDR mRNA and the degree of steatosis were found in NAFL patients." (PMID 37175993, 2023).
dyslipidaemia (6 papers, 2018 to 2025). "In obese women, it proposes that ANGPTL8 has a potential role in dyslipidaemia, and is intimately related to HDL." (PMID 32069954, 2020). "The results from the present study that ANGPTL8 was positively correlated with TG and negatively correlated with HDL in diabetic patients implied that ANGPTL8 could make a partial contribution to dyslipidaemia by affecting lipid metabolism." (PMID 32746907, 2020).
systemic inflammatory response syndrome (6 papers, 2017 to 2025). SIRS is a serious condition related to systemic inflammation, organ dysfunction, and organ failure. "The circulating ANGPTL8 levels in the serum of patients with systemic inflammatory response syndrome (SIRS) were also measured by the same group and found to be significantly higher, implying that ANGPTL8 reduces the acute phase of the inflammatory response." (PMID 36983346, 2023). "Third, we measured the circulating ANGPTL8 level in the blood of two groups of patients with systemic inflammatory response syndrome." (PMID 29255244, 2017). "Circulating ANGPTL8 has been reported to be augmented in systemic inflammatory response syndrome (SIRS), T2D, atherosclerosis, and NAFLD." (PMID 40427505, 2025). "The same group also assayed the circulating ANGPTL8 levels in the serum of patients with systemic inflammatory response syndrome (SIRS) and found that the levels were significantly increased, suggesting that ANGPTL8 diminishes acute phase of the inflammatory response." (PMID 32456228, 2020).
Glucose intolerance (5 papers, 2017 to 2025). Glucose intolerance (GI) can be defined as dysglycemia that comprises both prediabetes and diabetes. "Serum ANGPTL8 might play a role in the pathological mechanism of glucose intolerance." (PMID 29082263, 2017).
hypothyroidism (5 papers, 2019 to 2024). Abnormally low levels of thyroid hormone. "In hypothyroidism, thyroid stimulation hormone (TSH) is favorably linked with glycated hemoglobin (HbA1c), triglyscride (TG), TyG index, BMI, WC, leptin, ANGPTL8, hs-CRP, and IR." (PMID 39252284, 2024). "According to the reports, the circulating levels of ANGPTL8 were significantly increased under the status of hypothyroidism, which has also been confirmed to be positively correlated with serum concentrations of TG and TC." (PMID 34784265, 2022).
liver cancer (5 papers, 2021 to 2025). An epithelial or non-epithelial malignant neoplasm that arises from the liver. "An integrated computational analysis revealed that 4 SNPs in ANGPTL8 were predicted to be involved in large intestine, breast, and liver cancer." (PMID 38107478, 2023). "Clinical investigations have identified elevated serum ANGPTL8 levels in individuals with liver fibrosis and liver cancer." (PMID 38107478, 2023). "ANGPTL8 is secreted by the liver and acts as an inflammatory factor in the pathophysiology of liver cancer." (PMID 38107478, 2023). "The results of the Pathology Atlas also showed that ANGPTL8/betatrophin was enriched in liver cancer across 17 cancer types." (PMID 34646087, 2021).
Impaired glucose tolerance (4 papers, 2020 to 2023). An abnormal resistance to glucose, i.e., a reduction in the ability to maintain glucose levels in the blood stream within normal limits following oral or intravenous administration of glucose. "Bioinformatics analysis showed that Arg59Trp substitution caused by T allele, which has been shown to reduce the stability of ANGPTL8 protein, were associated with an increased risk of T2DM or impaired glucose tolerance." (PMID 34582711, 2021).
renal dysfunction (4 papers, 2018 to 2023). "The present study showed that ANGPTL8 was inversely correlated with eGFR and independently associated with renal dysfunction in diabetic patients, consistent with previous publications, and might also contribute to all-cause mortality." (PMID 32746907, 2020). "Binary logistic regression analysis showed that elevated ANGPTL8 levels were associated with greater risk ratios (RRs) of death (RR in quartile 4 vs. quartile 1, 3.54; 95% CI 1.32–9.50) and renal dysfunction (RR in quartile 4 vs. quartile 1, 12.43; 95% CI 1.48–104.81) only in diabetic patients." (PMID 32746907, 2020). "Increasing quartiles of ANGPTL8 were associated with elevated incidences of death and renal dysfunction in the diabetic patients (all p values < 0.05) but not in the control subjects." (PMID 32746907, 2020).
type 1 diabetes (4 papers, 2016 to 2020). "In type 1 diabetes mellitus (T1DM) and insulin-deficient animals, serum ANGPTL8 levels were increased." (PMID 31346314, 2019). "However, the majority of data showed that ANGPTL8 was increased in type 1 diabetes as well as T2D including our recent data where we used over 1600 subjects to show that ANGPTL8 was increased in T2D." (PMID 26784326, 2016).
breast invasive carcinoma (3 papers, 2021 to 2023). "GEPIA also showed that expression of ANGPTL8 remains downregulated in three cancers: CHOL; glioblastoma (GBM); and breast invasive carcinoma (BRCA)." (PMID 37375208, 2023).
cardiomyopathy (3 papers, 2016 to 2025). A disease of the heart muscle or myocardium proper. "Specifically, Angptl8 reverses established cardiomyopathy by the activation of the PirB receptor on the cell membrane of resident adult cardiac progenitor cells." (PMID 31388006, 2019). "Specifically, Angptl8 reverses established cardiomyopathy by PirB receptor activation on the cell membrane of resident adult cardiac progenitor cells." (PMID 31388006, 2019). "In this study, we employed UTMD to deliver the ANGPTL8 gene to the liver of rats with established cardiomyopathy induced by adriamycin." (PMID 27823982, 2016). "UTMD-mediated delivery of ANGPTL8 reversed established ADM cardiomyopathy." (PMID 40959490, 2025). "We found that hepatic overexpression of ANGPTL8 can reverse established cardiomyopathy." (PMID 27823982, 2016). "The exact molecular mechanism by which ANGPTL8 activated these quiescent adult cardiac progenitor cells in adult hearts with established ADM cardiomyopathy is also not known." (PMID 27823982, 2016). "However, under established cardiomyopathy induced by ADM, PirB was rarely seen, after reversal of ADM cardiomyopathy by ANGPTL8 gene liver delivery, PirB was again seen on the surface of membrane of cardiac muscle cells." (PMID 27823982, 2016).
intervertebral disc degeneration (3 papers, 2020 to 2023). "Previous studies found a positive association between ANGPTL8 expression and degenerative grades of intervertebral disc degeneration." (PMID 32034642, 2020). "Another group suggested that ANGPTL8 promoted ECM degradation and inflammatory cytokine release through activating the NF-κB signaling pathway which displays the detrimental role of ANGPTL8 in intervertebral disc degeneration (IDD)." (PMID 37947641, 2023).
lipid metabolism disorders (3 papers, 2021 to 2024). "To investigate the relationship between ANGPTL8 expression and lipid metabolism disorders in the liver during sepsis, we first detected the expression of ANGPTL8 in the liver and the plasma ANGPTL8 concentration in septic mice and control mice." (PMID 39019343, 2024). "Similar conclusions were shown in this study, and we found lipid metabolism related genes, including Angptl4, Mrap, Angptl8, and C1qtnf3, were significantly changed by disruption, suggesting that disruption induced lipid metabolism disorders in the myocardium." (PMID 33842566, 2021). "Additionally, three genes associated with lipid metabolism (Angptl8, Gadd45a, and Mid1ip1) are significantly downregulated in CD19−/− mice, providing further support for our argument that CD19−/− mice develop a lipid metabolic disorder." (PMID 35082296, 2022).
morbid obesity (3 papers, 2019 to 2021). An excess of body weight, normally defined as an individual with a body mass index greater than 35 or a body weight greater than one hundred percent of ideal body weight. "The presence of ANGPTL8 in the human liver was evaluated in liver biopsies (n = 74) obtained from patients with morbid obesity by immunohistochemistry and real-time PCR." (PMID 34884755, 2021). "In summary, our data suggests that ANGPTL8 plasmatic levels do not change significantly in patients with morbid obesity, although there is a modest difference related to gender that we cannot explain with the current studies." (PMID 32069954, 2020). "In addition, although morbid obesity seems to be accompanied by an increase in the presence of ANGPTL8 in the adipose visceral tissue, this morbid obesity does not appear to be a relevant factor involved in the regulation of changes in mRNA for the ANGPTL8 synthesis in these cells." (PMID 32069954, 2020).
prediabetes (3 papers, 2017 to 2020). "Although we found elevated serum ANGPTL8 in prediabetes and T2DM and the association between serum ANGPTL8 and other metabolic parameters, it was hard to decide the cause-and-effect relationship between them." (PMID 29082263, 2017). "The effect of cold on plasma ANGPTL8 levels was significantly different between the young, healthy, lean men and the middle-aged men with overweight and prediabetes (+28% vs. +3%, p < 0.01)." (PMID 31416197, 2019). "We, therefore, investigated the effect of short-term cooling on plasma ANGPTL3 and ANGPTL8, in comparison with ANGPTL4, in relation to changes in lipid metabolism in young, healthy, lean men as well as middle-aged men with overweight and prediabetes." (PMID 31416197, 2019). "Therefore, we speculate that the absent cold-induced changes in ANGPTL3 and ANGPTL8 in middle-aged men with overweight and prediabetes might reflect an attempt of the body to overcome impaired glucose uptake by insulin-resistant BAT." (PMID 31416197, 2019). "In middle-aged men with overweight and prediabetes, short-term cooling only significantly increased plasma ANGPTL4 levels (+15%, p < 0.05), but not ANGPTL3 (230 ± 9 vs. 251 ± 13 ng/mL, p = 0.051) or ANGPTL8 (2.2 ± 0.5 vs. 2.3 ± 0.5 μg/mL, p = 0.46)." (PMID 31416197, 2019).